ISG15 (ISG15 ubiquitin like modifier)
Diseases named in the same sentence as ISG15 in open-access papers (continued):
Sharing a sentence is not in itself a finding about the gene and the disease.
tumor (continued). "Spearman correlation analysis showed a strong negative correlation between the effect of oHSV1-FLT3L on the rank-based AUC of the tumor cell growth and expression of RIG-I (r = −0.6727; p = 0.0277), ISG15 (r = −0.6909; p = 0.0226), and OAS1 (r = −0.6636; p = 0.0306; data not shown)." (PMID 40955425, 2025). "Four types of PSCs (CCL19+, ISG15+, PLXDC1+, and MYH11+) were identified as TPSCs with high RO/E scores in tumor tissues, while remained three PSC subclusters were identified as CPSCs, mainly in the control pancreas and persist in tumor tissues." (PMID 40091495, 2025). "Therefore, the increased expression of ISG15 can effectively reduce the expression of ABCC2 and improve the sensitivity of tumor cells to cisplatin." (PMID 41193953, 2025). "In addition, comparative experiments are needed to explore the interaction mechanism of bacterial presence with immune (CD45 and CD68) or tumor cells (IFI6 and ISG15) based on the existing findings of marker expression correlations." (PMID 38548720, 2024). "Furthermore, IF staining of irinotecan-treated tumor tissue sections showed elevated OPN, PD-L1, p21Cip1, c-Myc, p65 (NF-κB), ISG15, and survivin, along with lower CyclinD1 compared to the untreated group." (PMID 39456585, 2024). "This analysis revealed that seven cell populations exhibited a significant correlation with poorer patient outcomes, including tumor cell cluster 3 (highly expressing S100A2), cluster 8 (TK1), cluster 10 (PTTG1), cluster 12 (IGFBP5), cluster 13 (ISG15), cluster 16 (UPP1), cluster 17 (IL13RA2)." (PMID 38331898, 2024). "In addition, knockdown of ISG15 or using the ISG15 inhibitor, DAP5, in combination therapy with carboplatin showed to improve the platinum sensitivity in‐vitro and reduce tumour burden in‐vivo." (PMID 38939897, 2024). "Intriguingly, there was a positive correlation between the expansion scores of ISG-15+CD8+ T cells and the levels of EBV DNA copy numbers, indicating that ISG-15+CD8+ T cells may have important functions in the immune response against tumours." (PMID 37735150, 2023). "The difference observed in the Lm-LLO-ISG15 versus Control Lm in vivo, but not in the in vitro studies, indicates that ISG15 provides a therapeutic target and is important to elicit an anti-tumor response in syngeneic CRC mouse models." (PMID 36831577, 2023). "CD8+ TMs expressing CCL5 and GZMA, MAIT (mucosal‐associated invariant T) cells expressing TCF7 and PLAC8, and CD4+ TNs (Naïve T cells) expressing CCR7 appeared in paratumour tissues, while CD4+ISG+ T cells expressing ISG15/20 and CD8+ TNs expressing TCF7 only appeared in tumour tissues." (PMID 36855810, 2023). "Then, we performed immunofluorescence staining on the normal lung, primary tumor, and metastatic lung sections using the markers of Tppp3+ monocytes (LY6C and TPPP3), Isg15+ macrophages (F4/80 and ISG15), Ifit3+ neutrophils (MPO and IFIT3), and Il12b+ DCs (CD11c and IL12B)." (PMID 37483625, 2023). "Re-emerged clonotypes of pre-existing ISG-15+CD8+ T cells could be found after treatment, which gives rise to a CXCL13-expressing effector population in responsive EBV (+) tumours." (PMID 37735150, 2023). "Together, these results indicate that depletion of USP18 in myeloid cells enhances anti-tumor immune responses, which is not due to the increased protein modification by ISG15 and is likely related to the increased IFN-I response in the TME." (PMID 38100351, 2023). "The analysis revealed that although some patients had low or negative PD-L1 expression in their tumour tissue, anti-PD-L1 antibody therapy was still effective in achieving complete clinical remission due to their high ISG15 expression." (PMID 37217923, 2023). "PD-L1 instability induced by elevated ISG15 improved PD-L1-targeted immunotherapy and inhibited LLC tumor growth in vivo, suggesting a possible strategy to target PD-L1-mediated immune escape of tumor cells." (PMID 37217923, 2023).
tumor (continued). "The results from MMTV-PyVT mice show that TPPP3+ monocytes, ISG15+ macrophages, IFIT3+ neutrophils, and IL12B+ DCs are mainly present in the tumor-reprogrammed lung microenvironment, and the metastasis-associated myeloid subpopulations are validated at the protein level." (PMID 37483625, 2023). "Normal and tumour tissues from such patients were analysed by qRT-PCR for the following 12 genes; six from RNA-seq: CLDN1, MAGEB2, CD24, CEACAM6, IL1B and ISG15 and six from RNA-seq and proteomics cross-linking: AKR1C3, TNFAIP2, RAB7A, LGALS3BP, PSCA and SSRP1." (PMID 36428603, 2022). "IFN-mediated ISG15 expression is regulated by NFkB, retinoic acid, and JNK in tumor cells." (PMID 35159348, 2022). "Macrophage in this cluster had high expression of type I interferon signaling related genes (IFITM3, IFI27, MX1, IFI6, and ISG15) as well as gene features related to immunosuppressive phenotype (APOE, APOC1, S100A9, and GPNMB), whereby participating in tumor immune regulation." (PMID 35265520, 2022). "Single-cell dataset revealed an enrichment of multiple efferocytosis-related genes in distinct myeloid subsets within the tumor, specifically, SPP1+, ISG15+, C1QC+ macrophages, and CD14+ monocytes in the tumors, which were distinct from the scRNA-Seq from the peripheral blood." (PMID 36439171, 2022). "High expression of ISG15 protein was significantly associated with LVI positivity and other features of poor prognosis including younger age at diagnosis, larger tumour size, high grade, poor NPI, lack of expression of ER and PR and HER2 positivity." (PMID 33073304, 2021). "Immunolocalization of ISG15 and CD8+ tumor infiltrating lymphocytes in 150 HGSOC samples showed a significant positive correlation between numbers of intratumoral CD8+ lymphocytes and ISG15 expression in the epithelial component of the tumor tissue." (PMID 30469497, 2018). "Unlike its definite anti-viral capacity, the role of ISG15 in tumor development remains controversial." (PMID 26919245, 2016). "ISG15 knockdown also downregulates the transcription of p21, a key tumor suppressor and negative modulator of cell cycle progress." (PMID 27659523, 2016). "ISG15 mRNA expression was significantly higher in HBV-related non-tumor tissues compared to non-HBV-related non-tumor tissues (P = 0.016)." (PMID 27626177, 2016). "The mean of ISG15 mRNA expression in liver tumor tissues was higher than in adjacent non-tumor tissues (not significant)." (PMID 27626177, 2016). "Furthermore, using anti-ISG15 antibody clearly indicated ISG15 protein overexpression in HCC cells and tumor tissues from patients." (PMID 25238261, 2014). "Because ISG15 interferes with ubiquitylation in tumor cells, it prompted us to test the possibility that ATM may regulate the ubiquitin/26S proteasome pathway through suppression of ISG15." (PMID 21298066, 2011). "However, ISG15+ CD68+ macrophages were not increased in tumours with ICI treatment when compared to treated‐naïve tumours, suggesting they were not dominant in the IFN‐γ response in the TME." (PMID 39934971, 2025). "ISG15 is regarded as a critical proto-oncoprotein that enhances the proliferation and metastasis of TNBC via inhibiting ubiquitin pathway, and may also mediate tumor immunity via the JAK/STAT signaling pathway." (PMID 40904511, 2025). "Thus, dual targeting of ISG15 and HMGCR via our nanoplatform triggers a metabolic trap: while accumulated cholesterol transiently supports survival, the collapse of intermediate flux cripples CSC maintenance and tumor growth." (PMID 41366470, 2025). "In ADU-S100 + anti-ISG15 treated tumors, we observed an increase in the frequency of central memory CD4+ and CD8+ T cells in addition to an increase in effector CD4+ T cell content vs. ADU-S100 treatment alone, suggestive of enhanced anti-tumor T cell activity in situ." (PMID 38312842, 2024).
tumor (continued). "Additionally, USP18 may target PD-L1 through ISG15 and inhibit the growth of CRC in vivo, suggesting a potential strategy for targeting PD-L1-mediated immune escape in tumor cells." (PMID 39334957, 2024). "However, it cannot be asserted that free-ISG15 always plays an anti-tumour role as it has also been observed to have a pro-oncogenic effect by increasing ERK1/2 phosphorylation in pancreatic cancer, promoting tumour stemness." (PMID 38400136, 2024). "Although we observed an increase in inflammatory, anti-tumor myeloid cells, we also noted an increase in M-MDSCs in the B16 model after combined treatment with ADU-S100 and either anti-PD-L1 or anti-ISG15, indicating that regulatory/tolerogenic mechanisms may remain in play." (PMID 38312842, 2024). "However, like tumor cells, T cells also produce significant amounts of ISG15; thus the extent of cell-autonomous versus cell-nonautonomous impact of ISG15 on T cell functionality requires further understanding." (PMID 38781019, 2024). "The induction in ISG15 by L1 was dependent on the NF-κB pathway and ISG15 was detected in CRC tumor tissue and in the adjacent stroma, but not in normal colonic mucosa, suggesting that ISG15 could serve as a therapeutic target for CRC treatment." (PMID 33228199, 2020). "Strong immunostaining of the entire tumor tissue for ISG15 was observed in poorly differentiated areas in 3 of 39 of the cases (red arrows), while the normal mucosa did not display significant staining for ISG15." (PMID 31903170, 2019). "In addition, they found that the ubiquitin conjugating enzyme E2 S (UBE2S, formerly E2-EPF) was a significant predictor of tumor burden, whereas ISG15 was not." (PMID 27626310, 2016). "ISG15 mRNA expression was quantified by qRT-PCR in 36 tumor and adjacent non-tumor tissues." (PMID 27626177, 2016). "A significant increase in anti-NK cell positive staining (brown color) was found in ZR/control shRNA xenograft tumor sections but no apparent NK cell staining in ZR/ISG15 shRNA xenograft tumors, ruling out cross-reaction of the anti-NK cell-specific immunoprobe with the tumor sections." (PMID 25749047, 2015). "Ipilimumab may also rescue tumor-impaired IFN-γ pathways in CD4+ T cells, since a number of genes associated with IFN-γ signals such as STAT1, ISG15, GBp1, and EIF2AK2 were up-regulated by ipilimumab (data not shown)." (PMID 22788688, 2012). "Interestingly, a significant fraction of ISG15 protein was localised to the nuclei of tumour cells, whereas no nuclear ISG15 staining was observed in ISG15-positive stromal cells." (PMID 16641915, 2006). "Moreover, in addition to tumor tissues, HMGA1 and ISG15 were also upregulated in hepatic and renal steatosis, suggesting a correlation between fat accumulation and HMGA1‐ISG15 levels may exist in multiple tissues and diseases." (PMID 40126377, 2025). "However, LAG-3 retention may render the ISG-15+CD8+ T cells into a terminal exhaustion state in non-responsive EBV (+) tumours." (PMID 37735150, 2023). "Thus, ISG15 presenting greater prognostic value in M-SFT patients may indicate its involvement in dedifferentiation and stemness processes and might function at latter stages of this tumour development." (PMID 35864381, 2022). "Therefore, whether ISG15 is a tumor promoter or a tumor suppressor has not yet been fully established." (PMID 26919245, 2016). "Despite these data were not related to an increased IFNG mRNA expression in tumor tissues, an activation of the canonical IFN-γ signaling pathway was demonstrated with an increased Stat1 phosphorylation and ISG15 expression." (PMID 40393975, 2025). "Our analyses showed that both tumor and nontumor cells expressed IFN signaling genes such as STAT1, STAT2, ISG15, OAS1, and MX1 in all three datasets." (PMID 34771447, 2021).
tumor (continued). "In non-tumor tissues from HCC patients, ISG15 mRNA expression was increased in HBV compared to non-HBV infection (P = 0.016)." (PMID 27626177, 2016). "ISG15 mRNA level of fifty pairs of human HCC samples and their non-tumor counterparts were analyzed, which was 2.4 to 4.2 folds higher in HCC specimens (P < 0.01)." (PMID 25238261, 2014). "ISG15 mRNA levels in HCC cells and tumor tissues from patients are higher than non-HCC cell and HCC adjacent tissues." (PMID 25238261, 2014). "However, here we found that ISG15-RAGE-driven activation of NF-κB and STAT3 promotes the invasiveness and metastasis of peri-necroptotic cells, but not cell proliferation and primary tumor growth." (PMID 38926796, 2024). "Moreover, ISG15-depleted necroptotic DAMPs failed to induce NF-κB and STAT3 activation and tumor-cell EMT." (PMID 38926796, 2024). "To further validate our hypothesis that the therapeutic efficacy of Lm-LLO-ISG15 in CRC is mediated by the generation of an ISG15-specific anti-tumor immune response, we compared the anti-cancer potency of Lm-LLO-ISG15 with a Control Lm, i.e., a Listeria vaccine that does not secrete ISG15." (PMID 36831577, 2023).
cancer (153 papers, 2006 to 2026). A tumor composed of atypical neoplastic, often pleomorphic cells that invade other tissues. "Taking together, we conclude that there is a significant correlation between ISG15 expression and prognosis, and in most cancer types, higher ISG15 expression is associated with poor prognosis." (PMID 40208307, 2025). "Changes in the ISG15 pathway are associated with a number of diseases, including cancer, neurodegenerative disorders, infection, and inflammation." (PMID 40774387, 2025). "For instance, within the realm of cancer biology, ISG15/ISGylation has been implicated in reinforcing ATG7 stability, thereby enhancing autophagy in pancreatic cancer cells – a mechanism that fosters tumour progression and therapeutic resistance." (PMID 40462493, 2025). "Multi-scale analysis was performed to explore the difference of cancer-associated fibroblasts (CAFs) in two groups and further identified ISG15 as a key driver biomarker." (PMID 40904511, 2025). "Overexpression of ISG15 promotes K48-linked ubiquitination and glycosylation-dependent proteasome degradation of PD-L1, improving the efficacy of PD-L1-targeted cancer immunotherapy." (PMID 40103488, 2025). "The ISG15 pathway is implicated in various diseases, including cancer and inflammatory disorders, but understanding its precise roles has been challenging because of limited availability of tools to study ISG15 biology." (PMID 40774387, 2025). "Conversely, aberrant activation of the ISG15/ISGylation pathway has been associated with promoting cancer cell proliferation, migration and invasion, underscoring its dualistic nature in oncogenesis." (PMID 40462493, 2025). "Numerous studies have elucidated the cancer-causing function of ISG15 in different types of tumors, like breast cancer, esophageal squamous cell carcinoma, hepatocellular carcinoma, nasopharyngeal carcinoma, pancreatic cancer, and ovarian tumor." (PMID 38951255, 2024). "Interferon‐Stimulated Gene 15 (ISG15) is emerging as an important oncogene and a potential diagnostic and therapeutic target for cancer." (PMID 38939897, 2024). "Our research confirmed the role of ISG15 as a cancer-causing gene in ccRCC and conducted a comprehensive analysis to identify its specific mechanisms." (PMID 38951255, 2024). "The ISG15, which was implicated in the pathogenesis of cancer, formed covalent bonds with its target substrates using a cascade of enzymes (E1, E2, and E3)." (PMID 36969077, 2023). "Numerous proteins have been identified as substrates of ISG15 and have been linked to the regulation of diverse cellular processes involved in cancer progression." (PMID 38036512, 2023). "Interferon-stimulated gene 15 (ISG15) is emerging as an important oncoprotein with a potential diagnostic signature and therapeutic target for a multitude of cancer, including CRC." (PMID 36831577, 2023). "The role of ISG15 has been associated with cellular processes such as protein translation, cytoskeleton dynamics, exosome secretion, autophagy, genome stability and cancer; therefore, it presents a potential target for therapeutic strategies." (PMID 34980152, 2022). "IRDS genes encode STAT1, as well as ISG15, which is overexpressed in diverse cancers and links chronic inflammation with DNA damage resistance." (PMID 35681561, 2022). "Our data are in accordance with the previous studies for ISG15 in BC which indicated that ISG15 is significantly associated with cancer development and metastasis." (PMID 33073304, 2021). "The obvious involvement of ISG15 in the cancer stem cell‐like features urged us to elucidate the mechanisms underlying regulation of ISG15 expression." (PMID 33797839, 2021). "The upregulation of ISG15 was identified as a critical gene strongly associated with BC progression and metastasis via modulating the cell architecture and enhancing the cancer cell motility." (PMID 33073304, 2021).